NGF (nerve growth factor)
Description:
Nerve growth factor is important for the development and maintenance of the sympathetic and sensory nervous systems. Extracellular ligand for the NTRK1 and NGFR receptors, activates cellular signaling cascades to regulate neuronal proliferation, differentiation and survival (Probable). The immature NGF precursor (proNGF) functions as a ligand for the heterodimeric receptor formed by SORCS2 and NGFR, and activates cellular signaling cascades that lead to inactivation of RAC1 and/or RAC2, reorganization of the actin cytoskeleton and neuronal growth cone collapse. In contrast to mature NGF, the precursor form (proNGF) promotes neuronal apoptosis (in vitro) (By similarity). Inhibits metalloproteinase-dependent proteolysis of platelet glycoprotein VI. Binds lysophosphatidylinositol and lysophosphatidylserine between the two chains of the homodimer. The lipid-bound form promotes histamine relase from mast cells, contrary to the lipid-free form (By similarity).
Synonyms: Beta-NGF; NGFB; HSAN5
Tractability: Small molecule: it belongs to a druggable protein family. Antibody: a drug acting on it is in phase 2 or 3 trials; UniProt places it where antibodies can reach, with high confidence; its Gene Ontology location is reachable by antibodies, with high confidence; UniProt predicts a signal peptide or a membrane-spanning region. PROTAC: a small molecule that binds it is known.
Target class: Secreted protein
Gene: Protein-coding gene on chromosome 1 (115,285,904 to 115,338,770, reverse strand). Ensembl gene ENSG00000134259.
Subcellular location: Secreted; Endosome lumen
Pathways (Reactome):
Signal Transduction: ARMS-mediated activation; Axonal growth stimulation; Ceramide signalling; Frs2-mediated activation; NADE modulates death signalling; NF-kB is activated and signals survival; NFG and proNGF binds to p75NTR; NGF processing; NRAGE signals death through JNK; NRIF signals cell death from the nucleus; PI3K/AKT activation; PLC-gamma1 signalling; Retrograde neurotrophin signalling; Signalling to RAS; Signalling to STAT3; Signalling to p38 via RIT and RIN; TRKA activation by NGF; p75NTR negatively regulates cell cycle via SC1; p75NTR recruits signalling complexes
Gene Ontology:
Molecular function: metalloendopeptidase inhibitor activity; protein binding; growth factor activity; nerve growth factor receptor binding; signaling receptor binding; transmembrane receptor protein tyrosine kinase activator activity
Biological process: extrinsic apoptotic signaling pathway via death domain receptors; neuron projection morphogenesis; positive regulation of gene expression; cell surface receptor protein tyrosine kinase signaling pathway; modulation of chemical synaptic transmission; negative regulation of cell population proliferation; negative regulation of neuron apoptotic process; nerve development; nerve growth factor signaling pathway; positive regulation of neuron differentiation; positive regulation of Ras protein signal transduction; circadian rhythm; neurotrophin TRK receptor signaling pathway; positive regulation of ERK1 and ERK2 cascade; positive regulation of phosphatidylinositol 3-kinase/protein kinase B signal transduction
Cellular component: extracellular region; cytosol; endosome lumen; Golgi lumen; synaptic vesicle
Genetic constraint (gnomAD): Loss-of-function variants: 4 observed, 13.66 expected, observed/expected ratio (o/e) 0.29, 90% interval 0.14 to 0.67. The upper end of that interval is the gene's LOEUF score, 0.67, which puts it in group 2 of 6, group 1 being the genes least tolerant of losing a copy. Missense variants: 283 observed, 346.34 expected, observed/expected ratio (o/e) 0.82, 90% interval 0.74 to 0.9. Synonymous variants: 140 observed, 137.71 expected, observed/expected ratio (o/e) 1.02, 90% interval 0.88 to 1.17.
Gene-disease validity (ClinGen):
ClinGen rates the evidence that NGF causes each of these diseases.
hereditary sensory and autonomic neuropathy (autosomal recessive): Strong. An instance of sensory peripheral neuropathy that is caused by an inherited modification of the individual's genome.
Homologues: Orthologues: macaque NGF (99% identical), pig NGF (93% identical), dog NGF (91% identical), guinea pig NGF (87% identical), rat Ngf (86% identical), mouse Ngf (85% identical), tropical clawed frog ngf (63% identical), rabbit NGF (53% identical), zebrafish ngfa (42% identical), zebrafish ngfb (42% identical). Paralogues in human: NTF3 (43% identical), BDNF (35% identical), NTF4 (30% identical).
Diseases named in the same sentence as NGF in open-access papers:
NGF is named in the same sentence as 603 diseases in open-access papers, as found by Europe PMC text mining. Sharing a sentence is not in itself a finding about the gene and the disease. The quoted sentences say what the papers report.
Alzheimer disease (181 papers, 2010 to 2026). A progressive, neurodegenerative disease characterized by loss of function and death of nerve cells in several areas of the brain leading to loss of cognitive function such as memory and language. "Dysregulation of the NGF/proNGF ratio has been associated with neurodegeneration in Alzheimer's disease (AD), positioning these neurotrophins as promising diagnostic biomarkers." (PMID 42169444, 2026). "For example, a clinical trial for Alzheimer’s disease where nerve-growth factor (NGF) was delivered via adeno-associated viral vectors (AAV2–NGF) failed due to the limited spread of AAV2-NGF to target cholinergic neurons." (PMID 41148193, 2025). "Recent literature highlights nerve growth factor (NGF) as a key neurotrophin potentially serving as a promising diagnostic biomarker for Alzheimer’s disease, frontotemporal dementia, malignancies and overactive bladder syndrome." (PMID 41471293, 2025). "Fahnestock & Shekari, (2019) found that pro-NGF levels were increased in the cortex and hippocampus regions of the brain in Alzheimer's disease due to cognitive impairment and neurodegeneration associated with this illness." (PMID 40924257, 2025). "NGF‐TrkA signaling is associated with the pathogenesis of Alzheimer's disease by modulating the metabolism of amyloid precursor protein and synaptic functions in cholinergic neurons." (PMID 38581121, 2024). "Pathological and mechanistic evidence suggests that loss of NGF signaling contributes significantly to the dysfunction of basal forebrain cholinergic neurons in Alzheimer’s disease." (PMID 38353689, 2024). "One of the initial clinical trials in gene therapy for Alzheimer’s disease involved introducing the gene encoding nerve growth factor (NGF) to the cholinergic nucleus basalis of Meynert." (PMID 38396996, 2024). "Nerve growth factor (NGF) loss is a potential factor for the degeneration of basal forebrain cholinergic neurons (BFCNs) in Alzheimer's disease (AD), and Rab5a is a key regulatory molecule of NGF signaling transduction." (PMID 38780008, 2024). "The 14-OH taxoids can act as nerve growth factor (NGF) mimetics, making them useful in the prevention of side effects associated with classical cytostatics (taxol, cisplatin, and vincristine) and Alzheimer’s disease." (PMID 36903424, 2023). "Functional NGF deficiency is believed to be associated with Alzheimer’s disease and plays a role in the pathogenesis of this condition." (PMID 37958943, 2023). "NGF is a neurotrophin implicated in regulating hippocampus-mediated memory storage in Alzheimer’s disease." (PMID 36176432, 2022). "NGF deficiency in the basal forebrain precedes degeneration of basal forebrain cholinergic neurons in Alzheimer's disease, contributing to memory decline." (PMID 31301255, 2019). "Particularly, it was shown that NGF rs6330*T minor allele is positively associated with the risk of migraine, schizophrenia and Alzheimer’s disease." (PMID 29499660, 2018). "Changes in NGF homeostasis in the brain, with particular regard to the ratio of NGF to proNGF levels, have also been linked to Alzheimer's disease." (PMID 29473218, 2018). "Nerve growth factor (NGF) is a neurotrophic factor relating to the causes of neurodegenerative diseases such as depression and Alzheimer’s disease." (PMID 27453720, 2016). "NGF is one of the key modulators of neurite outgrowth during development, and indeed many neurodegenerative diseases are associated with NGF insufficiency, e.g. depression and Alzheimer’s disease." (PMID 27685847, 2016). "NGF has been implicated in forebrain neuroprotection from amyloidogenesis and Alzheimer's disease (AD)." (PMID 27076121, 2016). "During Alzheimer’s disease (AD), plaques and tangles in the hippocampus disrupt the production, release, and uptake of NGF causing the atrophy and cell death of MS/DB cholinergic neurons." (PMID 30473908, 2014).
Alzheimer disease (continued). "In Alzheimer's disease, NGF has been shown to be effective in preventing the onset of the central cholinergic deficit, so the role of NGF in RGC degeneration caused by glaucoma is certainly worthy of further investigation." (PMID 25250333, 2014). "As for NGF precursor, it has been reported that its deficiency leads to a decrease in the expression of the low-affinity receptor p75NTR, thereby improving neurogenesis in Alzheimer’s disease." (PMID 41596330, 2026). "The wild-type *C allele for the NGF -198C/T polymorphism has been considered protective against multiple sclerosis in males, who show higher levels of NGF expression, while the Val allele for the NGF Ala35Val polymorphism represents a risk factor for the development of Alzheimer’s disease." (PMID 35746645, 2022). "Copper dyshomeostasis and mild acidic environment may modify the balance between metal, NGF, and Aβ, with consequences on the metal cellular uptake and therefore be among causes of the Alzheimer’s disease onset." (PMID 34064906, 2021). "Decreased NGF levels are associated with cognitive decline and Alzheimer’s disease." (PMID 33333870, 2020). "TrkA/NGF support neuronal health and function, and deficiencies in this axis are associated with progressive cholinergic neuron atrophy and death, and with cognitive deficit in disorders such as Down’s syndrome and Alzheimer’s disease." (PMID 31233568, 2019). "NGF has been shown to exert neuroprotective effects and even has been implicated in the treatment of chronic neurodegenerative diseases such as glaucoma and Alzheimer's disease." (PMID 24738070, 2014). "NGF is one of the key modulators of neurite outgrowth during development and into adulthood, many diseases of nervous system are associated with NGF insufficiency, especially some neurodegenerative diseases, for example, depression and Alzheimer's disease." (PMID 22761636, 2012). "Immunotherapies, including scFvs, are available for a diversity of neurological disorder targets such as semaphorin 4D (Huntington’s disease); nerve growth factor; tau; α-synuclein; and amyloid β (Alzheimer’s disease, ALS, Parkinson’s disease)." (PMID 40643474, 2025). "A decrease in NGF expression in cholinergic neurons can lead to cell senescence and death, resulting in a decline in cognitive function, suggesting that NGF plays a significant role in the progression of Alzheimer's disease (AD)." (PMID 40406043, 2025). "One study showed that when patients with Alzheimer's disease are given nerve growth factor (NGF) therapy, they experience characteristic trophic responses, which include axonal sprouting." (PMID 39712854, 2024). "Adeno-associated virus (AAV)-based gene delivery has also been used in patients affected by Alzheimer’s disease (AD) to deliver NGF to treat symptoms and progression." (PMID 39056738, 2024). "Nitrated proNGF is observed in the Alzheimer’s disease (AD) brain, indicating that studies on NGF nitration are also relevant to the precursor form." (PMID 38025269, 2023). "Studies have evidenced reduced levels of NGF in the basal forebrain in patients with Alzheimer’s disease." (PMID 37958943, 2023). "Cholinergic neurons require NGF for proper functioning and plasticity, and NGF metabolism is disrupted in Alzheimer’s disease." (PMID 37958943, 2023). "In the past, the study of these models showed that interfering with the NGF/proNGF balance can lead to neurodegeneration, suggesting a vicious cycle linking NGF dysmetabolism and Alzheimer’s disease-like neurodegeneration." (PMID 37143894, 2023). "This is of particular relevance for our study since changes in the ratio of proNGF/NGF can be found not only in AD11 mice but also in Alzheimer’s disease and in Down’s syndrome patients who develop AD with aging." (PMID 37143894, 2023).
Alzheimer disease (continued). "In this perspective, we will summarize the different approaches that have been used, or are currently applied, to deliver NGF to the brain, during preclinical and clinical trials to develop NGF as a therapeutic drug for Alzheimer’s disease." (PMID 35360160, 2022). "Exogenous nerve growth factor (NGF) improves the cholinergic neuron system and has therapeutic potential for neurodegenerative disorders such as Parkinson’s disease, Alzheimer’s disease, and diabetic polyneuropathy." (PMID 35336596, 2022). "Trials involving central administration of NGF to aid recovery after cerebral ischemia were preceded by its use in Parkinson's disease and Alzheimer's disease." (PMID 35283994, 2022). "NGF has been shown to slow or prevent neurodegenerative signals in Alzheimer’s Disease (AD) progression." (PMID 35327415, 2022). "The interaction of NGF with its high-affinity receptor TrkA mediates different cellular pathways related to Alzheimer’s disease, pain, ocular dysfunction, and cancer." (PMID 36139382, 2022). "Nerve growth factor (NGF) has emerged as a potential therapeutic agent in Alzheimer’s disease (AD) due to its regenerative effects on basal forebrain cholinergic neurons." (PMID 35557841, 2022). "Several studies pointed out that NGF promotes the survival of cholinergic neurons in Alzheimer’s disease (AD), although its use in the therapy of AD is limited by its poor metabolic stability and low blood-brain barrier permeability." (PMID 36139382, 2022). "Our study, in combination with this recent post-mortem observation, suggests that it is still too early to conclude that NGF therapy is ineffective for Alzheimer’s disease." (PMID 33723225, 2021). "Since the 1980s, the development of a pharmacology based on nerve growth factor (NGF) has been postulated for the therapy of Alzheimer’s disease (AD)." (PMID 34867367, 2021). "In Alzheimer’s disease (AD), basal forebrain cholinergic neurons (BFCNs) undergo progressive atrophy, suggesting a deficit in NGF trophic support." (PMID 34434101, 2021). "In Alzheimer’s disease, impaired nerve-growth factor (NGF) supply to cholinergic neurons leads to their degeneration, correlating with the cognitive decline of affected patients." (PMID 34064900, 2021). "This metabolic pathway, discovered by us and referred to as the NGF metabolic cascade, is described in detail in this review along with its marked dysregulation in the Alzheimer’s disease (AD) pathology." (PMID 35011577, 2021). "In this review, we discuss the history of NGF-dependency of BFCNs and the atrophy of these neurons in Alzheimer’s disease (AD)." (PMID 35011577, 2021). "SB100X was used to improve nerve growth factor (NGF) secretion by encapsulated cell biodelivery device in patients with mild to moderate Alzheimer’s disease." (PMID 32471151, 2020). "In Alzheimer’s disease, abnormal regulation and insufficient supply of NGF have been regarded as a crucial pathological process." (PMID 33364963, 2020). "In another modality of protection against Alzheimer’s disease, HE has been shown to stimulate the synthesis of nerve growth factor (NGF) in cultured astrocytes." (PMID 32244920, 2020). "A similar NGF encapsulation strategy exploiting emulsification has been advocated to promote survival of cholinergic neurons: implantation of NGF-loaded microspheres into the brain improved spatial learning and memory in the rat model of Alzheimer’s disease." (PMID 33375672, 2020). "Numerous clinical trials are attempting to improve the delivery of NGF to neural tissues in the brain to enhance the therapeutic effect of Alzheimer’s disease treatment." (PMID 33333870, 2020). "In Alzheimer’s Disease models based on NGF-stimulated PC12 cells and primary cerebral cortex neurons, MALAT1 inhibits neuron apoptosis and neuroinflammation, while it stimulates neurite outgrowth via miR-125b-regulated PGTS2, CKD5, and FOXA1 expression." (PMID 33192306, 2020).